CGA (glycoprotein hormones, alpha polypeptide)
Diseases named in the same sentence as CGA in open-access papers (continued):
Sharing a sentence is not in itself a finding about the gene and the disease.
neuroendocrine carcinoma (continued). "The histology showed gallbladder adenocarcinoma, with a single focus of neuroendocrine carcinoma (NEC) component of less than 30%; Ki-67 index > 80%, synaptophysin (Syn) (+), chromogranin A (CgA) (+), and clusters of differentiation (CD) 56 (+) (T2bN1M0, Stage IIIB)." (PMID 34767241, 2022). "In the remaining 16 CgA-negative patients, however, only two were poorly- differentiated neuroendocrine carcinomas." (PMID 26911576, 2016). "However, the biological features of PCa with the expression of neuroendocrine markers, such as CgA, but not with neuroendocrine carcinoma morphology or t-NEPC features, still needs to be characterized." (PMID 37240468, 2023).
pheochromocytoma (25 papers, 1996 to 2025). "Although several studies have shown that CgA is a reliable sensitive marker for the diagnosis of pheochromocytoma, its diagnostic specificity is quite poor." (PMID 24523932, 2014). "A positive correlation was found between CgA and WE-14 concentrations in the plasma of patients with pheochromocytoma in which high plasma levels of CgA are associated with high levels of WE-14 (r = 0.717, p<0.001, n = 37)." (PMID 24523932, 2014). "In conclusion, CgA determination showed high sensitivity in identifying gastroenteropancreatic tumours and, in association with catecholamines, in detecting patients with phaeochromocytoma." (PMID 11237384, 2001). "Our data suggested that EM66 could potentially be a new diagnostic and prognostic marker of pheochromocytomas, and that, besides CgA, other granin-derived peptides, such as EM66, could represent valuable supplementary markers for the management and follow-up of these tumors." (PMID 24523932, 2014). "CgA is abnormally expressed in a variety of tumors, such as pheochromocytoma, small-cell lung cancer, medullary thyroid carcinoma, pancreatic islet cell tumors, and prostate cancers." (PMID 39975592, 2025). "Most reported cases involve invasive ductal carcinoma, and IHC panels typically include markers such as SYN and CgA for pheochromocytoma, and ER, PR, HER2, GATA3, and mammaglobin A for breast carcinoma." (PMID 40746928, 2025). "Similar stimulation experiments performed in PC12 cells (derived from pheochromocytoma of the rat adrenal medulla), another cell line frequently used to study the regulated pathway, even showed less than twofold stimulation of CgA secretion." (PMID 35086936, 2022). "We observed that CgA positive cells were present in both pheochromocytomas (esPHEO_T1 and PHEO_T), but ACTH positive cells were only observed in the rare pheochromocytoma (esPHEO_T1) with the ACTH-secreting cellular characteristics." (PMID 34905486, 2021). "CgA was first isolated from chromaffin cells of the adrenal medulla, and CgB was initially characterized in a rat pheochromocytoma cell line." (PMID 34204153, 2021). "In particular, plasma CgA concentrations increase by 12.5-fold in patients with pheochromocytoma compared with normal men." (PMID 34204153, 2021). "Elevated serum CgA levels were reported in 100% of gastrinomas, 89% of pheochromocytomas, 80% of carcinoids, 50% of medullary thyroid carcinomas, and in 69% of non-functioning Pan-NETs, respectively." (PMID 32020844, 2020). "Collectively, our data show that combined CgA and granin-derived peptide test assays should possibly improve the diagnosis of pheochromocytoma." (PMID 24523932, 2014). "In conclusion, we have shown that the CgA-derived peptide WE-14 represents a potential sensitive marker for the diagnosis and follow-up of pheochromocytoma." (PMID 24523932, 2014). "Currently, biochemical tests used for the diagnosis of pheochromocytoma include the measurement of plasma or urinary catecholamine metabolites (metanephrine, normetanephrine, methoxytyramine) and CgA assay." (PMID 24523932, 2014). "Currently, CgA is widely used as a marker for pheochromocytoma and several CgA assays are commercially available." (PMID 24523932, 2014). "Plasma CgA and catecholamines identified 13 and 18 out of 20 phaeochromocytomas with sensitivity of 65% and 90%, respectively." (PMID 11237384, 2001). "The structure of circulating chromogranin A (CgA) of phaeochromocytoma patients was characterised and compared with that of CgA extracted from tumours." (PMID 8611427, 1996). "Our aim was to investigate circulating miRNA expression profiles in pancreatic neuroendocrine tumors (pNET) and pheochromocytomas/paragangliomas (PPGL) to find miRNAs which could be used as biomarkers along with CgA in these patients." (PMID 32887459, 2020).
pheochromocytoma (continued). "In addition, in association with other biological markers, such as CgA and/or EM66, WE-14 measurement systematically improves the diagnostic sensitivity for pheochromocytoma." (PMID 24523932, 2014). "Pheochromocytomas and abdominal paragangliomas stain positive for neuroendocrine markers CgA, SYP, ISL1, INSM1 and, often, GATA3; subsets of cases may display an intricate network of supporting sustentacular cells which are highlighted by an S100 or SOX10 stain." (PMID 37685605, 2023). "In addition to EM66, we have also reported that WE-14, a 14 amino-acid peptide derived from the proteolytic processing of CgA (CgA324-337) occurs in normal and tumoral (i.e. pheochromocytoma) human adrenochromaffin tissues and that this peptide is secreted from pheochromocytes in primary culture." (PMID 24523932, 2014). "In several NETs, such as pheochromocytomas, paragangliomas, carcinoid syndrome, the islet of Langerhans cell tumors of the pancreas, medullary thyroid cancer and parathyroid and pituitary adenomas, plasma CgA levels may be high, although this is much less common (60%) in SCLC." (PMID 37568540, 2023). "An elevated level of circulating CgA has been associated with almost all tumor types of the neuroendocrine system, but its sensitivity varies between 47–100% depending on tumor type (100%, in gastrinomas, ~89% in pheochromocytomas, and ~69% in nonfunctioning pNETs)." (PMID 32887459, 2020). "For all patients (n = 37), whatever the test combination performed (WE-14 + CgA, WE-14 + EM66, or CgA + EM66), the sensitivity for the diagnosis of pheochromocytoma was increased (to approximately 90%) compared to each test alone." (PMID 24523932, 2014). "A positive correlation was found between WE-14 and EM66 or between CgA and EM66 concentrations in plasma of patients with pheochromocytoma (r = 0.509 and r = 0.470, respectively; p<0.01, n = 37) (data not shown)." (PMID 24523932, 2014). "Immunohistochemistry demonstrated that the pheochromocytoma cells were positive for chromogranin A (CgA) and synaptophysin (SYN), and negative for cytokeratin (CK), GATA3, and ER (-, 5)." (PMID 40746928, 2025). "The initial diagnosis of pheochromocytoma was also ruled out based on the absence of a zellballen pattern, negative CgA staining, and normal catecholamine levels." (PMID 38518040, 2024). "The negative staining for chromogranin A (CgA) ruled out pheochromocytoma, while the absence of melan-A, inhibin, and calretinin excluded adrenocortical tumors." (PMID 39493270, 2024). "Pheochromocytoma was excluded by: negative immunohistochemistry for Syn and CgA, negativity for OCT3/4 and no lack of INI-1." (PMID 37495956, 2023). "Immunostaining of COX4I2, CgA and α-SMA were performed in the same area of pheochromocytoma tissue." (PMID 36172142, 2022). "Thus, at the clinical stage, our histopathology results confirmed that Case 1 was a rare ectopic ACTH secreting pheochromocytoma which stained positively for both ACTH and CgA." (PMID 34905486, 2021). "Serum CgA levels were reportedly elevated in 100% of gastrinomas, 89% of pheochromocytomas, 80% of small intestinal carcinoids, 69% of non-functioning pancreatic NETs (Pan-NETs), and 50% of MTCs, in which tumor growth paralleled to serum CgA levels." (PMID 33485291, 2021). "CgA readily distinguishes pheochromocytomas and paragangliomas from tumours that are not neuroendocrine." (PMID 28155290, 2017). "The aim of the present study was to investigate the tumoral chromogranin A (CgA)-derived peptide WE-14 and the potential advantage to combine plasma WE-14 detection with the EM66 assay and the existing current CgA assay for the diagnosis of pheochromocytoma." (PMID 24523932, 2014). "Immunoreactivity to classic neuroendocrine markers such as CgA and synaptophysin is almost always present, and second-generation neuroendocrine markers ISL LIM Homeobox 1 (ISL1) and INSM1 have also been found as reliable markers of an adrenal medullary origin in pheochromocytoma." (PMID 35205664, 2022).
pheochromocytoma (continued). "The baseline serum CgA levels were elevated in 103 of 208 patients (50%) with various NETs, including carcinoid tumors, insulinomas, gastrinomas, non-functioning Pan-NETs, pheochromocytomas, medullary thyroid tumors, neuroblastomas, Merkel cell tumors, and pituitary adenomas." (PMID 32020844, 2020). "Thus, an IHC panel can be helpful to identify pheochromocytoma cells that are positive for CgA, SYN and CD56, but negative for CK." (PMID 31109373, 2019). "Therefore, we could not compare the results from the combined measurements of CgA, WE-14 and EM66 to the gold standard for the diagnosis of pheochromocytoma." (PMID 24523932, 2014).
Hypertension (24 papers, 2001 to 2025). The presence of chronic increased pressure in the systemic arterial system. "Many other clinical conditions, such as kidney failure, liver cirrhosis, arterial hypertension, or chronic heart failure, can also cause increased CgA values." (PMID 38136263, 2023). "To find out the mechanisms underlying spontaneous reversal of hypertension in CgA-KO mice, we focused on global transcriptome changes in the livers of 0.5-, 1- and 2-year-old WT and CgA-KO mice by RNA-seq." (PMID 36440192, 2022). "The present study shows that while aging caused hypertension in WT mice, high BP in 0.5-year-old CgA-KO mice was spontaneously reversed in 2-year-old CgA-KO mice." (PMID 36440192, 2022). "Previous studies have shown that genetic polymorphisms of CgA, CgB, and CgC are associated with hypertension." (PMID 34204153, 2021). "A recent study suggests that a common genetic variant of the CgA-derived peptide catestatin is associated with hypertension and atherogenesis." (PMID 34204153, 2021). "O'Connor's group was the first to report that circulating levels of CgA are associated with hypertension." (PMID 31588572, 2019). "Reduced blood levels of anti-angiogenic CgA peptides were associated with vascular remodelling in the groups of patients on PPIs and with arterial hypertension." (PMID 27531191, 2016). "Arterial hypertension has a complex relationship with the CgA system, as hypertensive patients have higher levels of total CgA, but deletion of the CgA gene causes development of arterial hypertension in mice." (PMID 27531191, 2016). "We found that arterial hypertension was associated with higher levels of CgA-FR and VS-1 in TA, and that a normotensive or hypertensive status influenced the link between the CgA system and inflammation in TA." (PMID 27531191, 2016). "Taking advantage of the Chromogranin A (CgA) knockout (CgA-KO) mouse as a model for healthy aging, we have identified Vsig4 (V-set and immunoglobulin domain containing 4) as the critical checkpoint gene in offsetting age-associated hypertension and diabetes." (PMID 36440192, 2022). "However, circulating CgA is affected by a number of diseases and medications, such as hypertension, heart failure, renal failure,and inflammatory bowel disease, and the use of proton pump inhibitors can cause an elevation of circulating CgA, which would be a confounding factor in the clinical work." (PMID 39975592, 2025). "CgA itself has been implicated in numerous physiological processes: it is believed to play a role in secretory granule biogenesis, support immune activity, serve as a valid neuroendocrine marker, and to influence the course of cardiovascular disorders such as hypertension." (PMID 34620125, 2021). "CgA-KO mice have been characterized with hypertension, elevated sympathoneuronal activity and affected endocrine cells in the adrenal gland and pancreas." (PMID 41298823, 2025). "Those outcomes confirm those of previous CST-hypertension-based studies, according to which CgA levels are increased in hypertensive patients, while CST protein level is diminished." (PMID 38473713, 2024). "Elevated plasma levels of CgA have been observed in patients with CVD and hypertension, while low CST levels are linked to essential hypertension." (PMID 39337398, 2024). "The current study examined the pro-hormone Chromogranin A (CgA), as this protein regulates both hypertension and diabetes." (PMID 36440192, 2022). "The CgA-KO mice display two opposite aging phenotypes: hypertension but heightened insulin sensitivity at young age, whereas the blood pressure normalizes at older age and insulin sensitivity further improves." (PMID 36440192, 2022). "We focus our discussion on the role of CgA in inflammation, glucose metabolism, hypertension, and mitochondrial health, in the context of aging-related regulation of gut permeability on the spread of bacterial DNA and levels of Vsig4/CRIg." (PMID 36440192, 2022).
Hypertension (continued). "The reversal of hypertension in aging CgA-KO mice likely stems from (i) low accumulation of microbial DNA, (ii) decreased spillover of norepinephrine in the heart and kidneys, and (iii) reduced inflammation." (PMID 36440192, 2022). "Circulating CgA levels are high in hypertension, CAD, and heart failure that show increments in the sympathetic tone and adrenomedullary system activity." (PMID 34204153, 2021). "CgA-knockout mice reveal hypertension, high plasma catecholamine and adiponectin levels, and lower interleukin-6 and lipid levels compared with wild type mice." (PMID 34204153, 2021). "Plasma levels of CgA, catestatin, and pancreastatin are significantly increased in patients with hypertension compared with healthy control subjects." (PMID 34204153, 2021). "Plasma CgA levels are increased in patients with hypertension, coronary heart disease, and heart failure." (PMID 34204153, 2021). "CgA and derived polypeptides are the convincing biomarkers for atherosclerosis, diabetes, hypertension, and cardiovascular diseases." (PMID 34204153, 2021). "In human essential hypertension, CgA has been shown to be elevated while catestatin has been shown to be diminished." (PMID 32758260, 2020). "CgA knockout mice (Chga-KO) display: (i) hypertension with increased plasma catecholamines, (ii) obesity, (iii) improved hepatic insulin sensitivity, and (iv) muscle insulin resistance." (PMID 28228748, 2017). "Correlation studies show that variables related to disease phenotype (e.g. arterial hypertension), anti-rheumatic drugs and other supportive medications (e.g. PPIs) influence the CgA system and impact on its relationship with inflammation." (PMID 27531191, 2016). "Treatment with proton-pump inhibitors (PPIs) and arterial hypertension partially accounted for CgA levels and high inter-patient variability." (PMID 27531191, 2016). "Targetedablation of CgA locus in a mouse model results in severe hypertension that can berescued by administration of the catestatin fragment." (PMID 24671122, 2014). "In humans,naturally occurring variation at the CgA gene contributes toalterations in autonomic function, and hence hypertension, as a consequence ofchanges in storage and release of CgA." (PMID 24671122, 2014). "Given the importance of CgA in inflammation, insulin sensitivity and hypertension – and the strong correlation of these metabolic orders with neurodegeneration – we hypothesize that CgA may play a significant role in neurodegeneration." (PMID 40393970, 2025). "Recently, clinical studies have suggested that CgA may be involved in cardiovascular pathologies, including hypertension, heart failure, myocardial infarction, and acute coronary syndromes." (PMID 34356287, 2021). "Therefore, CgA is a biomarker for atherosclerosis, diabetes, hypertension, and coronary heart disease." (PMID 34204153, 2021). "There is a possibility that local processing of CgA may result in the inhibition of inflammatory processes and prevent hypoxia-mediated hypertension and proteinuria." (PMID 34620125, 2021). "In addition, the Gly364Ser genetic variant of catestatin seems to offerprotection against the development of hypertension, whereas the CgA processing to catestatin appears to bemore effective in women than in men." (PMID 24671122, 2014). "Specificity of CgA in patients with essential hypertension was 98%." (PMID 11237384, 2001). "It has been demonstrated that CgA knockout mice developed high blood pressure, which could effectively be treated with replacement therapy of catestatin, indicating a potential novel target for treatment of hypertension." (PMID 37762872, 2023). "Therefore, we asked whether decreased spillover of norepinephrine (NE) in heart and kidney could explain spontaneous reversal of hypertension in aging CgA-KO mice." (PMID 36440192, 2022). "Moreover, CgA-knockout (CgA-KO) mice develop an obese phenotype as well as severe hypertension which could be rescued by intra-peritoneal injections of CST." (PMID 30337922, 2018).
Hypertension (continued). "A lack of catestatin in CgA knockout mice caused elevated blood pressure values, which could effectively be treated by supplementation with catestatin, thus indicating potential therapeutic effects of catestatin for treatment of hypertension." (PMID 37762872, 2023). "Such a holistic approach may shed light on the physiological pathways of CgA processing and yield new insights into the role of the CST in the development of human hypertension." (PMID 38473713, 2024). "Since CgA is even more stable compared with cathecholamines in the circulating blood, its plasma levels reflect the sympathetic tone and adrenomedullary system activity, which are altered in coronary artery disease (CAD), heart failure, and hypertension." (PMID 34204153, 2021). "CgA and its fragments can be detected in the blood of patients of various non-cancer diseases, such as heart failure, hypertension, thyroid disease, renal failure, liver disease, inflammatory bowel disease, rheumatoid disease, and cancers." (PMID 34868938, 2021). "Similar CgA439/CgAtot, CgA-FRs/CgAtot and VS-1/CgAtot were observed in the presence or the absence of arterial hypertension in the whole sample and after stratification for PPI therapy." (PMID 27531191, 2016). "Increased blood levels of CgA have been shown in numerous inflammatory and non-inflammatory conditions, including neuroendocrine tumours, renal failure, arterial hypertension, chronic heart failure and rheumatoid arthritis." (PMID 27531191, 2016). "Patients on conventional immunosuppressive agents had higher CgA-FRs, and the difference was maintained after stratification for PPIs or for arterial hypertension (data not shown)." (PMID 27531191, 2016). "Both CgA-KO and CST-KO mice developed hypertension due to the absence of CST, as evidenced by the normalization of blood pressure upon CST supplementation." (PMID 41298823, 2025).